LCN2 (lipocalin 2)
Diseases named in the same sentence as LCN2 in open-access papers (continued):
Sharing a sentence is not in itself a finding about the gene and the disease.
tumor (continued). "However, our in vitro data confirm that instead of cancer cells themselves, neutrophils, especially those co-cultured with cancer cells, are the major source of LCN2 and may contribute to the abundant LCN2 in tumor foci." (PMID 31500632, 2019). "However, the Lcn2 expression of tumor cells was very individual, and without association with the proliferating tumor cell fraction or apoptotic tumor cell fraction." (PMID 31413815, 2019). "However, it is still unknown how tumor cells selectively take up iron-loaded Lcn-2 relative to iron-free Lcn-2 or how the latter is antagonized within tumor cells in order to avoid its reported apoptotic effects." (PMID 30641920, 2019). "Moreover, we proposed that iron might be the missing link to understand the tumor-promoting role of Lcn-2." (PMID 30641920, 2019). "Some of these genes could be involved in tumor development such as LCN2." (PMID 30559930, 2018). "However, PDAC patients at the time of diagnosis had advanced disease with substantial weight; furthermore, LCN2 could play a major role in tumor progression in the early stages compared to the advanced stages." (PMID 30366466, 2018). "On the other hand, LCN2 has immune-modulatory effects itself which may help to limit tumor growth." (PMID 30534534, 2018). "In addition, because TCF7L1 overexpression seems to have a paracrine effect on proliferation in vivo and that LCN2 is a secreted protein overexpressed in many types of cancer, we surmise that TCF7L1 may drive tumor growth through induction of LCN2." (PMID 28467300, 2017). "Therefore, we speculate that dying tumor cells educate macrophages at core tumor regions in order to access additional iron via Lcn-2." (PMID 28979267, 2017). "However, the molecular mechanism underlying the upregulation of LCN2 in tumor cells has not been fully illustrated." (PMID 29098164, 2017). "Therefore, the elevated expression of LCN2 may confer a stem cell nature to tumor cells, possibly via the PI3K-Akt pathway." (PMID 27168162, 2016). "Therefore, downregulation of those 3 molecules (Lyve1, Prom1, Lcn2) could be responsible for lower migration capabilities of tumor (metastatic) cells in AMEC-KO mice." (PMID 27640364, 2016). "Furthermore, the expression patterns of LCN2 paralleled the levels of HIF-1α in tumor cells." (PMID 25467539, 2014). "From these results, the cellular source of Lcn2 may be from hypoxic tumor cells." (PMID 25467539, 2014). "Therefore, to determine whether LCN2 transcript levels would increase in hypoxic tumoral regions, we analyzed the mRNA levels of LCN2 in HIF-1α-positive regions of tumor tissues by real-time RT-PCR." (PMID 25467539, 2014). "Furthermore, LCN2 mRNA levels were significantly higher in the B16-F1 cells and various human tumor cells cultured under hypoxic conditions than in cells cultured under normoxic conditions, while no changes in mRNA expression were observed in nontumor NIH-3T3 cells, even under hypoxic conditions." (PMID 25467539, 2014). "Recent findings suggest possible mechanisms underlying lipocalin-2 function in tumorigenesis, such as promoting the epithelial-mesenchymal transition (EMT), regulating the iron homeostasis in cancer cells, affecting on steroid-dependent tumor growth and modulating MMP-9 activity." (PMID 22640376, 2012). "Here, we hypothesize that the tumor cell UPR regulates Lcn2 production." (PMID 21649922, 2011). "Therefore, the effect of lipocalin 2 on tumor metastasis depended on the tumor-type specificity." (PMID 19077278, 2008). "ST analysis showed widespread NETs distribution in tumor tissues, with NETs-related markers S100A8, FUT4, LCN2, S100A9, and HSP3A exhibiting high expression across tissue regions." (PMID 41488283, 2026). "It further highlights Lcn2+ neutrophils and Ccl2+ fibroblasts as potential therapeutic targets for improving CAR-T cell anti-tumor efficacy." (PMID 40568084, 2025).
tumor (continued). "LCN2 also promotes VEGF-mediated lymphangiogenesis and tumor metastasis via epithelial–mesenchymal transition (EMT)." (PMID 40472740, 2025). "In turn, TANs release proteases, such as MMP-9 and lipocalin-2 (LCN2) to degrade the extracellular matrix (ECM) and disrupt the BBB, thereby enabling tumor cell extravasation." (PMID 41219968, 2025). "Lipid metabolism also facilitates immune escape, tumor cells utilize FABP4-mediated lipid droplet storage for energy reserves and secrete lipocalin-2 (LCN2) to polarize macrophages toward an M2 immunosuppressive phenotype." (PMID 40438103, 2025). "Overall, these findings demonstrate that tumor cell‐derived CCL5 is a key mediator of macrophage activation and lymphatic metastasis induced by LCN2 silencing in GC." (PMID 40884261, 2025). "Therapeutically, treatment of PC9-BM LCN2-high BM-bearing mice with SH4-54, bevacizumab, or a combination of both significantly suppressed tumor progression and prolonged OS." (PMID 41436606, 2025). "This PMN stimulates the secretion of STAT3‐activated lipocalin 2 (LCN2), a secretory glycoprotein, from the N2‐neutrophils, thus triggering MET of tumor cells, consequently facilitating their colonization and metastatic expansion." (PMID 40470380, 2025). "Beyond its role in fibroblast activation, LCN2 regulates several oncogenic signaling pathways—including PI3K/AKT, STAT3, ERK/MAPK, NF-κB, and Wnt/β-catenin—that collectively promote tumor proliferation, immune evasion, and extracellular matrix remodeling." (PMID 40472740, 2025). "In the tumor region, DEGs included ECM-related genes such as MMP7, LCN2, chemokine CXCL5, and tumor markers CLDN4 and MUC4." (PMID 40303346, 2025). "To elucidate the role of LCN2 in WTX-L-mediated GC ferroptosis in vivo, we overexpressed LCN2 in MKN45.shWTX-L GC cells and then determined tumor growth." (PMID 40109379, 2025). "Tumors from TSK mice also had a higher neutrophil-to-lymphocyte ratio, which was validated by immunohistochemical analysis of tumor sections stained with antibodies specific for T cells (CD3), NK cells (NKR), and neutrophils (LCN2)." (PMID 41008788, 2025). "Future research should focus on developing EGFRvIII-targeting approaches, including mRNA vaccines and LCN2/STAT3 inhibitors, while exploring combination therapies that simultaneously address tumor-intrinsic and TME-mediated mechanisms." (PMID 40472740, 2025). "Taken together, these data argue that LCN2 represents an important, tumor-exploited iron trafficking axis that complements canonical TFR1/DMT1 routes and should be considered when assessing tumor iron biology and designing iron-targeted interventions." (PMID 41190142, 2025). "Our findings revealed a downregulation of LCN-2 and an upregulation of MMP-9 gene expression in tumor tissues compared to healthy counterparts." (PMID 40214460, 2025). "Tumor-specific stem-like cells (tSTM, cluster 0) exhibited strong upregulation of OLFM4, LEFTY1, SOD3, LCN2, SLC12A2, and MMP7, consistent with proliferative, inflammatory, and invasive phenotypes." (PMID 41282138, 2025). "LCN2, a confirmed oncogene in CRC, and CEACAM5, a common tumor marker in CRC diagnosis and treatment, both showed significantly increased expression along the continuum (p < 0.05)." (PMID 39456726, 2024). "This transformation, coupled with the MMP-9 x LCN2 complex, enables the cells to remodel their surrounding ECM and enhance tumor cell invasion." (PMID 39188682, 2024). "Macrophage-derived LCN2 is crucial for iron transport into the TME, significantly enhancing tumor cell proliferation." (PMID 39188682, 2024). "Cytokines secreted by the tumor microenvironment, such as IL-1β and TNF-α, stimulate the transcription of LCN2." (PMID 38673873, 2024). "Box plots showed that the expression of LYZ, LCN2, and CEACAM5 from external datasets was significantly higher in tumor samples compared to normal samples (p < 0.01), complementing our findings." (PMID 39456726, 2024).
tumor (continued). "Studies have demonstrated that LCN2 interacts with MMP9 to form complexes, exerting pro-angiogenic and pro-tumor effects." (PMID 38694500, 2024). "Further immunohistochemical staining confirmed the inhibition of LCN2 expression in the NPs-siLCN2 group, and the levels of p-EGFR and the tumor proliferation index Ki67 were also decreased." (PMID 36899380, 2023). "In prostate cancer cells, LCN2 played an important role in facilitating cell migration and invasion by inducing EMT, leading to increased tumor invasion." (PMID 36926025, 2023). "Previous studies have reported that LCN2 and MMP9 form a heterodimer through disulfide bonding to protect MMP9 enzyme activity, contributing greatly to tumour invasion and metastasis." (PMID 37753805, 2023). "Targeted inhibition of LCN2 by anti-LCN2 monoclonal antibody (3D12B2) increases intracellular iron levels, decreases GPX4 expression, and induces ferroptosis in tumor cells, thereby overcoming resistance." (PMID 38273826, 2023). "Indeed, the uptake of dead tumor cells, which died due to apoptotic, accidental necrotic and necroptotic cell death induced by professional phagocytes, results in a functional shift towards an alternative (M2-like) phenotype, coinciding with the stimulation of the expression and secretion of Lcn-2." (PMID 37958332, 2023). "Some studies have revealed a high level of LCN-2 expression in patients with inflammatory breast cancer (IBC) and that it is essential for tumor growth and skin invasion in mice with IBC." (PMID 36718277, 2023). "Gain‐of‐function experiments of SERPINA3 and LCN2 in the horizontal co‐culture system and NICO‐1 and mouse xenograft experiments showed osteogenic and tumor‐suppressive roles in PCa." (PMID 37408474, 2023). "Evidence from preclinical studies is most supportive of tumor-modulating roles for insulin, CCK, and Lcn2, whereas data are less conclusive for the adipokines leptin and adiponectin, despite correlations from human epidemiologic studies." (PMID 37648285, 2023). "By the uptake and recycling of heme-bound iron these macrophages may further contribute to tumor growth and development, promoting iron release towards cancer cells via high expression of the iron exporter ferroportin and the iron-transporting protein lipocalin-2 (LCN-2)." (PMID 36986429, 2023). "Some of these characteristics arise from the ability of LCN2 to facilitate iron uptake into cancer cells or its ability to form a heterodimer with matrix metalloprotease (MMP)-9, which contributes to tumor progression and metastasis." (PMID 36926025, 2023). "Nevertheless, we provide evidence that LCN2/LOXL2, LCN2/MMP9, LOXL2/MMP9, and LLM affect tumour growth and progression in a synergistic manner." (PMID 37753805, 2023). "Lastly, it has been shown that tumour cells in CSF express the iron-binding protein lipocalin-2 (LCN2) and its receptor SCL22A17 to outcompete other cells, such as macrophages, for free iron and thus ensure tumour metabolism." (PMID 37511202, 2023). "However, our study demonstrated that LCN2 functioned as an iron-disturbing factor to not only induce T-cell apoptosis but also to remove iron from the T cells for use by the tumor cells, thereby enhancing tumor cell proliferation and promoting tumor progression." (PMID 38072118, 2023). "LCN2 (gene family name Lcn2), which binds to iron-loaded catecholate through the LCN2 receptor (LCN2R), increases intracellular iron to protect tumor cells from ROS-induced damage and apoptosis." (PMID 37994159, 2023). "When correlation analysis was carried out in tumor samples, SLC22A17 was negatively correlated with both LCN2 and MMP9, showing few correlation pairs compared to those obtained for normal samples." (PMID 36211450, 2022). "Our results demonstrated that LCN2 and MMP9 were mainly upregulated in most tumor types, whereas SLC22A17 was largely downregulated, representing a specific hallmark signature for all gastrointestinal tumors." (PMID 36211450, 2022).
tumor (continued). "From our data, there are some indications that LCN2 can lead to enhanced activation of pro-MMP-9, thereby causing a higher degree of extracellular proteolysis, leading to the tumor-promoting effect of positive co-regulation of MMP-9 and LCN2 by ADAM8." (PMID 35216088, 2022). "When tumor cells were co-cultured with macrophages (THP-1 cells), expression of LCN2 and MMP-9 in ADAM8 KO cells was induced, suggesting that macrophage signaling can overcome ADAM8-dependent intracellular signaling in PDAC cells." (PMID 35216088, 2022). "On these bases, the role of LCN2, SLC22A17, and MMP9 was evaluated in different tumor types performing in silico analysis using the expression and methylation data available on TCGA and GTEx datasets." (PMID 36211450, 2022). "This analysis allowed us to identify the median levels of LCN2, SLC22A17, and MMP9 genes and isoforms of each tumor type that were upper to 3rd or lower to 1st quartiles of corresponding normal tissue." (PMID 36211450, 2022). "While high-fat feeding resulted in accelerated tumor formation rates, this was prevented by depletion of either CLDN1 or LCN2." (PMID 35013251, 2022). "Examples of genes with more expression per cell in the erlotinib-treated group are PLAAT3, LCN2, CEBPD, and SAA1; conversely, LDHB is shown as an example for transcripts more abundant in control tumor cells." (PMID 36482068, 2022). "Several lines of evidence show that depending on the cell type and the tumor microenvironment (TME), LCN2 has pleiotropic effects and can either act as a tumor promoter or as a suppressor of tumorigenesis." (PMID 35053376, 2022). "The results indicated that the expression of the LCN2 gene (ENSG00000148346.11) and all its isoforms was upregulated in tumor samples compared to normal tissues." (PMID 36211450, 2022). "We here develop a novel cancer therapy named Ferroptosis ASsassinates Tumor (FAST) by combining iron oxide nanoparticles with cancer-selective knockdown of seven key ferroptosis-resistant genes (FPN, LCN2, FTH1, FSP1, GPX4, SLC7A11, NRF2)." (PMID 36329436, 2022). "Consistently, the in vivo anti-tumor effects of CUDC-907 accompanied by the downregulated expression of p-mTOR and LCN2 and upregulated expression of p-IRE1α and LC3B-II were evaluated in a xenograft mouse model." (PMID 35989326, 2022). "On this basis, we conducted an in silico study to evaluate the role of LCN2, SLC22A17, and MMP9 genes and related isoforms in different tumor types by following specific workflow steps." (PMID 36211450, 2022). "Tumor cells in chemo-resistant samples showed higher expression of chemoresistance and proliferation related genes (FN1, LCN2, CD44, FEN1)." (PMID 36248860, 2022). "The correlation analysis was also carried out between the methylation levels and expression of LCN2, SLC22A17, and MMP9 in each tumor type." (PMID 36211450, 2022). "Survival analysis was performed using Xena UCSC, retrieving the log-rank test values and p-values calculated for the CG probesets related to LCN2, SLC22A17, and MMP9 in each tumor type." (PMID 36211450, 2022). "Numerous changes based on HGFL-RON signaling are downregulated (e.g., lipocalin-2 [LCN2]) and a few upregulated (regenerating family member 3 gammas [Reg3G]) in tumor cells." (PMID 35626096, 2022). "Overall, differential analysis revealed that LCN2 and MMP9 were widely upregulated in several tumor types, while an opposite trend was observed for SLC22A17, suggesting its potential role in tumor suppression." (PMID 36211450, 2022). "Previous studies have shown that low expression of LCN2, ATM, and ATP1 increases the sensitivity of tumor cells to cisplatin." (PMID 36016575, 2022). "IFI27, LCN2, GAST, and SERPINA1 were downregulated after NACT in tumor cells, while OLFM4, MRPS35, MMP1 and MED21 were upregulated in tumor cells." (PMID 36474268, 2022).
tumor (continued). "Depletion of LCN2 in IBC cell lines reduced colony formation, migration, and cancer stem cell populations in vitro and inhibited tumor growth, skin invasion, and brain metastasis in mouse models of IBC." (PMID 34342930, 2021). "In conclusion, TAMs favor tumor lymphangiogenesis and their subsequent lymph node metastasis, either by secreted factors (VEGF-C, VEGF-D, and LCN2) or by integration of a subset of TAMs, called M-LECP, into lymphatic vessels." (PMID 33783686, 2021). "However, our data demonstrating higher levels of secreted LCN2 in IBC vs non‐IBC cell lines and showing significant inhibition of key IBC tumor features such as tumor emboli/skin invasion in LCN2‐silenced tumors suggest that LCN2 may exert its influence via an IBC‐specific mechanism." (PMID 34342930, 2021). "Since MMP-9 can degrade the extracellular matrix and basement membranes, LCN2 protects MMP-9 from degradation, thus increasing MMP-9 activity to contribute to tumor progression and metastasis through formation of an LCN2/MMP complex." (PMID 34202288, 2021). "LCN2 is upregulated in PDAC mouse models, correlates to decreased food intake, and its absence protects from tumor cachexia, presumably via a type 4 melanocortin receptor-mediated mechanism." (PMID 34680216, 2021). "Tumor hypoxia supports such an iron-donor phenotype by upregulating solute carrier family 40, member 1 (SLC40A1) and lipocalin 2 (LCN2) expression in TAMs, resulting in increased iron availability in the TME and improved iron uptake by malignant cells." (PMID 34603327, 2021). "Lcn2 overexpression in metastatic breast cancer (MBC) can lead to cancer progression by inducing the epithelial-to-mesenchymal transition and enhancing tumor angiogenesis." (PMID 33916786, 2021). "Studies have also indicated the tight relationship between high expression of LCN2 and EMT, invasion, and metastasis in several types of tumours." (PMID 34601488, 2021). "Overexpression of LCN2 in CRC cells suppressed proliferation, migration and invasion in vitro and tumor growth and metastasis in vivo." (PMID 32328462, 2020). "In tumour tissue, we observed equal and in most of the cases a higher number of overall LCN-2 reactivity, with the notion that staining of LCN-2 mRNA was even enhanced in high-grade tumours." (PMID 31772326, 2020). "Additionally, we identified a positive correlation between LCN2 and HIF-1A expression, which suggested that LCN2 may induce NPC radioresistance through regulating pathways associated with adaptation to hypoxia in the tumor microenvironment." (PMID 33604288, 2020). "Lipocalin 2 (LCN2), which belonged to the lipocalin superfamily the same as PTGDS, had been widely studied in various tumours." (PMID 32047563, 2020). "Other studies have shown that high levels of LCN2 correlate with epithelial-to-mesenchymal transition (EMT), invasion, and metastasis in different tumor types." (PMID 32575507, 2020). "LCN2 levels showed a similar pattern as CD177 staining, significantly higher in tumor foci than PCT and normal tissue (p < 0.001), although it was expressed not only in prostate stroma but also in epithelial cells in tumor foci (Orange)." (PMID 31500632, 2019). "Therefore, LCN2 could be used as a potential target for tumour chemosensitivity." (PMID 31819048, 2019). "In agreement with a potential cooperative role for both FABP1 and LCN2, previous work has identified FABP1 as a marker for circulating tumor cells (CTCs) in patients with advanced stage cancers." (PMID 31105883, 2019). "Other authors have described a gelatinase activity containing molecule of 130 kDa as Lipocalin-2/MMP-9 complex and contributed its function to inflammatory processes and tumour invasion." (PMID 31036020, 2019). "It has been shown that under hypoxic conditions, LCN2 expression is increased at HIF-1α-positive regions of tumors and parallels HIF-1α expression in those tumor cells." (PMID 30871254, 2019).